CST3 (cystatin C)
Diseases named in the same sentence as CST3 in open-access papers (continued):
Sharing a sentence is not in itself a finding about the gene and the disease.
chronic kidney disease (continued). "Recently, the 2021 Chronic Kidney Disease Epidemiology Collaboration (CKD-EPI) proposed the creatinine–cystatin C equation, which appears to be less influenced by ethnicity or muscle mass and may achieve greater accuracy and reduce clinical bias in estimating renal function." (PMID 36671416, 2022). "In this study, approximately two-fifths (37.9%) of the chronic kidney disease patients had normal serum creatinine levels and approximately four-fifths of these patients had elevated serum cystatin C. Moreover, none of the patients with elevated serum creatinine had normal cystatin C levels." (PMID 33401560, 2021). "The changes in renal function were evaluated by measurement of creatinine, cystatin-C, and the use of the Chronic Kidney Disease Epidemiology Collaboration (CKD-EPI) algorithm, and by the use of T-tests, repeated measures of variance and ANCOVA analyses." (PMID 33317156, 2020). "The agreement between cystatin-C and creatinine based eGFR before and after an exercise intervention in chronic kidney disease (CKD) patients is yet to be studied." (PMID 30563479, 2018). "In stable chronic kidney disease (CKD) patients, cystatin C in combination with creatinine better predicted measured GFR than either biomarker alone." (PMID 27293926, 2016). "Using cystatin C, associations were present in those with and without chronic kidney disease." (PMID 18681974, 2008). "Among the most widely adopted formulas are the Chronic Kidney Disease Epidemiology Collaboration (CKD-EPI) equations, which include creatinine-only, cystatin C-only, and the combined creatinine–cystatin C equation." (PMID 41516239, 2025). "In line with this, the recently published KDIGO guidelines for the management of chronic kidney disease recommend the use of a combined formula for the estimation of GFR, if cystatin C measurement is available." (PMID 39792299, 2025). "The eGFR was calculated using three methods based on the Chronic Kidney Disease Epidemiology Collaboration (CKD-EPI) formula: serum creatinine (eGFRcr), serum cystatin C (eGFRcys), and a combination of both (eGFRcrcys)." (PMID 41524038, 2025). "The 2021 Chronic Kidney Disease Epidemiology Collaboration (CKD-EPI) equation, which incorporates both creatinine and cystatin C, provides enhanced estimation of glomerular filtration rate (eGFR) compared to creatinine-only equations." (PMID 41209141, 2025). "Furthermore, cystatin C exhibits enhanced prognosticaccuracy for cardiovascular morbidity and mortality, especially in patients withchronic kidney disease (CKD), diabetes mellitus, atrial fibrillation, and ACS." (PMID 41209141, 2025). "Cystatin C–eGFR z-scores provide a developmentally appropriate, laboratory-based method to detect AKI and predict chronic kidney disease in neonates and infants." (PMID 41278334, 2025). "Serum cystatin C has already been used in CKD-EPI (chronic kidney disease epidemiology collaboration) equations, whereas penKid is a member of the enkephalins group, with concentrations in CSF (cerebrospinal fluid) 100 times higher than its serum concentrations." (PMID 38541160, 2024). "Cystatin C and kidney injury molecule-1 (KIM-1) are critical biomarkers that can complement NGAL in monitoring chronic kidney disease progression." (PMID 39728735, 2024). "In light of the evolving landscape of kidney disease research, it is pertinent to acknowledge the established role of biomarkers such as Cystatin C in the estimation of GFR, a cornerstone in the management of chronic kidney disease (CKD)." (PMID 38785547, 2024). "Owing to the high morbidity of cardiovascular diseases (CVD) in patients with chronic kidney disease (CKD), renal biomarkers such as beta-2-microglobulin (B2M), cystatin C and lipocalin-2 (LCN-2) have attracted increasing attention." (PMID 37155257, 2023).
chronic kidney disease (continued). "This study aimed to compare the cystatin C-derived estimated glomerular filtration rate (GFR) of the study groups and also, to correlate the clinical features of chronic kidney disease (CKD) with decreased GFR in children with sickle cell anaemia (SCA)." (PMID 38031035, 2023). "Are differences between estimated glomerular filtration rate by cystatin C (eGFRcys) vs creatinine (eGFRcr) associated with the risk of end-stage kidney disease (ESKD) and mortality among individuals with chronic kidney disease (CKD)?" (PMID 35175342, 2022). "We calculated eGFR using the chronic kidney disease epidemiology collaboration (CKD-EPI) creatinine (eGFRcrea) and creatinine–cystatin C (eGFRcrea–cys) formulas, and BMI from weight and height measurements." (PMID 35495025, 2022). "The Chronic Kidney Disease Epidemiology Collaboration (CKD-EPI) equations are based on creatinine alone (CKD-EPIcr), cystatin C alone (CKD-EPIcys) and combined creatinine and cystatin C (CKD-EPIcr-cys)." (PMID 36033773, 2022). "Three proteins (C1QTNF1, FGF-21 and CST3) were associated with incident HF among patients without bariatric surgery who retained excess body fat, suggesting that dyslipidemia and chronic kidney disease may constitute therapeutic targets to prevent the development of HF among patients with obesity." (PMID 35945262, 2022). "Renal function was assessed by glomerular filtration rate estimated using the combined Chronic Kidney Disease Epidemiology Collaboration (CKD‐EPI) equation with standardized serum creatinine (Cr) and non‐standardized serum cystatin C (CysC)." (PMID 34825788, 2022). "Chronic kidney disease (CKD) is a long-term structural or functional disorder of the kidneys, manifested by elevated serum levels of creatinine, cystatin C, or blood urea nitrogen." (PMID 33995050, 2021). "Additionally, cystatin C is a more sensitive marker of chronic kidney disease (CKD) than creatinine in many populations and CKD is a known risk factor for death after critical illness." (PMID 32653023, 2020). "One possible explanation is the rate of history of chronic kidney disease in the CRS1 group being higher than the non-CRS1group, as NGAL and cystatin C have been shown to be elevated in patients with chronic kidney disease." (PMID 33083054, 2020). "eGFR was calculated using chronic kidney disease epidemiology (CKD-EPI) equations based on serum creatinine (eGFRCKD-EPI-Cr), cystatin C (eGFRCKD-EPI-CysC), and joint equations (eGFRCKD-EPI-Cr-CysC), respectively." (PMID 31636737, 2019). "In the calculation of eGFR, several equations including the serum creatinine-based Modification of Diet in Renal Disease (MDRD) equation, Chronic Kidney Disease Epidemiology Collaboration (CKD-EPI) equation, and serum cystatin C-based equation are utilized." (PMID 29670671, 2018). "We compared chronic kidney disease (CKD) categorization using eGFRcr and cystatin C-based estimated GFR (eGFRcys) in an elderly, racially/ethnically diverse cohort to determine their concordance." (PMID 30427947, 2018). "In children with chronic kidney disease, thrombomodulin seems to be a valuable marker of endothelial dysfunction, correlating strongly with CKD stage, kidney function parameters (urea, creatinine, and cystatin C), as well as oxidative stress, hypertension, and left ventricular hypertrophy." (PMID 29682152, 2018). "Studies in chronic kidney disease (CKD) patients demonstrated that serum βTP is an adequate marker of glomerular filtration rate (GFR) impairment with a diagnostic accuracy similar to those of serum creatinine, cystatin C (Cys) and β2-microglobulin (β2M)." (PMID 28219328, 2017). "A total of 1042 patients were included in the final analysis (mean age 62.87 ± 10.35 years, mean creatinine clearance rate 75.12 ± 26.24 mL/min, and mean cystatin C 1.20 ± 0.47 mg/L), and 297(28.5%) patients presented with pre-existing chronic kidney disease (CKD), creatinine clearance <60 ml/min." (PMID 29312646, 2017).
chronic kidney disease (continued). "Using Chronic Kidney Disease Epidemiology Collaboration (CKD-EPI) equations, we compared GFR estimated from creatinine (eGFRcreat), cystatin C (eGFRcys), and both (eGFRcreat-cys) at baseline and over 5 years of follow-up." (PMID 29016597, 2017). "Serum creatinine, cystatin C, and KIM-1 concentrations were measured, and eGFR was calculated using the Chronic Kidney Disease Epidemiology Collaboration (CKD-EPI) creatinine–cystatin C equation, at baseline and last follow-up." (PMID 27858892, 2016). "In the studied group of children with chronic kidney disease a significant correlation between the concentrations of oxidized LDL and serum creatinine and cystatin C was demonstrated." (PMID 26885251, 2016). "Using the CKD-EPI (Chronic Kidney Disease Epidemiology Collaboration) equation, GFR was estimated from routinely measured cystatin C concentrations, examining all available samples per participant in one assay run." (PMID 26465150, 2015). "In summary we showed that using serum cystatin C as a predictor of GFR in estimation equations resulted in widely varying eGFR which significantly affected the identification and classification of chronic kidney disease." (PMID 24868463, 2014). "Nevertheless, it was shown that chronic kidney disease epidemiology collaboration (CKD-EPI) creatinine based formula and Hoek cystatin C based formula had the best correlation with 99mTc-DTPA in GFR of less than 15 cc/min." (PMID 23841035, 2013). "The meta-analysis involved studies with different definitions of chronic kidney disease as some of the studies used GFR <90 mLs/min, others used GFR <53 mLs/min and one study used cystatin C level above 1.03 mg/dL." (PMID 23094157, 2012). "Large prospective studies evaluating the accuracy of cystatin C in estimating glomerular filtration rate in populations with chronic kidney disease are lacking." (PMID 41586348, 2026). "Therefore, following the Chronic Kidney Disease Epidemiology Collaboration (CKD-EPI), we used the 2012 CKD-EPI Cystatin C equation to measure eGFR based on Cystatin C, age, and gender." (PMID 39882269, 2025). "Searches were performed in PubMed, Scopus, and Web of Science using combinations of keywords such as “cardiorenal syndrome,” “biomarkers,” “heart failure,” “acute kidney injury,” “chronic kidney disease,” and specific marker names (e.g., NGAL, KIM-1, cystatin C, CA125, bio-ADM, FGF-23, etc.)." (PMID 41157213, 2025). "Using a fixed normal limit rather than an age‐corrected normal material for p‐cystatin C or eGFRCYS will misclassify many individuals as having chronic kidney disease." (PMID 40356291, 2025). "Cystatin C was positively correlated with homocysteine levels in coronary artery disease patients without chronic kidney disease." (PMID 37587534, 2023). "In the present study, we assessed the predictive power of two other biomarkers, Cystatin-C (Cys-C) and Neutrophil Gelatinase-Associated Lipocalin (NGAL) for early detection of chronic kidney diseases (CKD) in the absence of a gold standard." (PMID 34466571, 2020). "We aimed to clarify the relationship between SUA levels and kidney function assessed by cystatin C in a Japanese general community population without chronic kidney disease (CKD)." (PMID 30940115, 2019). "Kidney function and chronic kidney disease (CKD) are commonly defined by glomerular filtration rate (GFR), usually estimated by one of several equations based on age, gender, race and serum creatinine and/or cystatin C." (PMID 28575141, 2017). "Our data do not support the use of cystatin C to confirm a diagnosis of chronic kidney disease in primary care." (PMID 29016597, 2017). "On the other hand, measurement of cystatin C is costly and eGFR based on cystatin C needs further validation across a broad spectrum of populations with or without chronic kidney disease." (PMID 25215234, 2014).
chronic kidney disease (continued). "The Chronic Kidney Disease Epidemiology Collaboration (CKD-EPI) reported two equations in 2012: one based on cystatin C concentration (CKD-EPI2012cys) and the other using both serum creatinine and cystatin C concentrations (CKD-EPI2012Scr-cys)." (PMID 24454737, 2014). "The interest of Serum cystatin C (ScysC) as an alternative –and somehow superior - GFR marker to serum creatinine has recently been highlighted in the general population and in patients with native chronic kidney disease (CKD)." (PMID 25495910, 2014). "Evaluations of serum cystatin C and serum creatinine were reported to predict cardiovascular events in elderly persons without chronic kidney disease." (PMID 24678413, 2014). "The primary outcome was chronic kidney disease (CKD), defined as creatinine- or cystatin C–based estimated glomerular filtration rate (eGFRcr and eGFRcys, respectively) <60 mL/min/1.73 m2 or urine albumin-creatinine ratio (UACR) ≥3.5 mg/mmol measured at age 60-64 years." (PMID 23714172, 2013). "High cystatin C levels are independently associated with cardiovascular risk factors such as BMI, low HDL cholesterol and smoking even in patients without chronic kidney disease or microalbuminuria." (PMID 22152087, 2011). "In addition, other international guidelines do not support the use of cystatin C measurement in chronic kidney disease management." (PMID 40257600, 2025). "Estimated glomerular filtration rate (eGFR)Cr-Cys, eGFRCr, and eGFRCys were calculated using Chronic Kidney Disease Epidemiology Collaboration or CKD-EPI equations based on both biomarkers (serum creatinine and serum cystatin C)." (PMID 41503314, 2025). "The leading examples are the Chronic Kidney Disease Epidemiology Collaboration (CKD-EPI) eGFR equations, which employ creatinine, age (A), sex (S), with or without race (R) [eGFRcr(ASR) or eGFRcr(AS)] or both creatinine and cystatin C [eGFRcr-cys(ASR) or eGFRcr-cys(AS)]." (PMID 37003973, 2023). "This study set out to compare the cystatin C-derived estimated glomerular filtration rate (GFR) of the study groups and also, to correlate the clinical features of chronic kidney disease (CKD) with decreased GFR in children with sickle cell anaemia." (PMID 38031035, 2023). "Third, cystatin C levels were measured only once; we could not discriminate whether an elevated cystatin C level was influenced by acute kidney injury or chronic kidney disease." (PMID 33466214, 2021). "The glomerular filtration rate, as estimated by the equation of the Chronic Kidney Disease Epidemiology Collaboration (GFR via CKD-EPI), creatinine, and cystatin C did not change relevantly during fasting (GFR: P = 0.584, creatinine: p = 0.060, and cystatin C: p = 0.073)." (PMID 34395487, 2021). "As these plasma biomarkers are not in steady state during critical illness, timing of creatinine and cystatin C measurements in this cohort do not allow for meaningful estimation of glomerular filtration rate or accurate classification of chronic kidney disease prior to study enrollment." (PMID 32653023, 2020). "NOMAS did not obtain repeated measures of serum creatinine or cystatin-C to document a decline in values over time, nor did we systematically determine whether participants progressed to end stage renal disease." (PMID 31940363, 2020). "The use of cystatin C to confirm a diagnosis of chronic kidney disease resulted in reclassification of a small proportion (7.7%) of people as not having chronic kidney disease, but a much greater proportion were reclassified as having more advanced disease (59%)." (PMID 29016597, 2017). "Also, in a pooled analysis of 3418 individuals with chronic kidney disease, percentages of estimated GFR within 30% of GFR for equations based on serum cystatin C alone, serum cystatin C, serum creatinine, or both levels with age, sex, and race were 81%, 83%, 85%, and 89%, respectively." (PMID 27069964, 2016).
chronic kidney disease (continued). "Although laboratories currently report eGFR from the MDRD equation, the MDRD equation may eventually be replaced by newer estimating equations, such as the Chronic Kidney Disease Epidemiology Collaboration (CKD-EPI) equation or estimates based on alternative biomarkers (e.g., cystatin-C)." (PMID 22788730, 2012). "After the rigorous review of more than 20 approaches, the NKF/ASN Task Force published the final report that recommended the implementation of the Chronic Kidney Disease Epidemiology Collaboration equation for eGFR using creatine and expanded utilization of cystatin C testing." (PMID 38250300, 2024). "We explored the association between the serum level of cystatin C (CysC) at admission and short‐term functional outcome in patients with hypertensive intracerebral hemorrhage (HICH) without chronic kidney disease (CKD)." (PMID 36545837, 2023). "Chronic kidney disease (CKD) is diagnosed based on the presence of kidney damage or a reduced glomerular filtration rate (GFR), as indicated by clinical markers such as serum creatinine or cystatin C." (PMID 38140298, 2023). "Therefore, it is a very useful biomarker in chronic kidney disease (CKD), and the GFR based on cystatin C is more specific." (PMID 35722493, 2022). "Although cystatin C has been proposed to be a better indicator than creatinine for IKF, previous studies support the use of the creatinine using Chronic Kidney Disease Epidemiology Collaboration (CKD-EPI) equation for routine clinical care among PLWH." (PMID 35300612, 2022). "The GFR was estimated using the Cockroft–Gault formula (abbreviated as creatinine clearance, CrCL), Chronic Kidney Disease Epidemiology Collaboration formula (CKD-EPI) featuring both creatinine and cystatin C, and the Modification of Diet in Renal Disease Study equation (MDRD)." (PMID 34903821, 2021). "However, more recent studies are supporting the use of the chronic kidney disease epidemiology collaboration cystatin C-based equations (both CKD-EPI-sCR-CysC and CKD-EPI-CysC)." (PMID 24877060, 2014). "Moreover, elevated cystatin C seems to have a link with the development of CVD in subjects without chronic kidney disease (CKD), and its level showed a strong correlation with the degree of CAD and all-cause mortality." (PMID 35889883, 2022). "Thus, studies with cystatin C (CisC), lipocalin-2 (NGAL), and microalbuminuria have shown that these are detected early during chronic kidney disease (CKD) diagnosis compared to seric creatinine and proteinuria, and indicate the location and severity of the kidney damage." (PMID 33061236, 2020). "Similar results were observed in analysis using the Chronic Kidney Disease Epidemiologic Collaboration (CKD-EPI) formulae for creatinine, cystatin C, and GFR combining creatinine and cystatin C (data not shown)." (PMID 28306749, 2017). "In similar, an analysis of the Chronic Renal Insufficiency Cohort study showed that the validity and precision of estimation of GFR from serum cystatin C were similar with those from creatinine, without the need to take into consideration either race or ancestry." (PMID 38351263, 2024). "Additional associations with diverse renal function measures (lower cystatin C and higher eGFRcreatinine-cystatin C levels) and a CUBN-focused GRS further suggests an important role of CUBN in the future personalization of chronic kidney disease management in people without diabetes." (PMID 36926036, 2023). "We measured GFR and compared the performance of the Modification of Diet in Renal Disease (MDRD), the Chronic Kidney Disease-Epidemiology Collaboration (CKD-Epi) and the Berlin Initiative Study (BIS) equations based on creatinine and/or cystatin C in octogenarians and nonagenarians." (PMID 24295505, 2013).
chronic kidney disease (continued). "Furthermore, since serum creatinine and cystatin C are commonly employed in clinical settings for evaluating renal function, the performance of the CCR and SI to predict sarcopenia was also investigated in patients with or without chronic kidney disease (CKD)." (PMID 38921440, 2024).